RUNX3 (RUNX family transcription factor 3)
Diseases named in the same sentence as RUNX3 in open-access papers (continued):
Sharing a sentence is not in itself a finding about the gene and the disease.
leukemia (continued). "Re-expression of WT but not KR mutant PKM2 inhibited the expression of RUNX1, but not the other core-binding factor family members RUNX2 or RUNX3 in NB4, U937 and 32DBCR-ABL leukemia cells, suggesting that SUMOylation of PKM2 is essential in modulating RUNX1." (PMID 33473116, 2021).
asthma (24 papers, 2009 to 2025). "Among the phenotypes associated with polymorphisms in the RUNX3 gene locus are ankylosing spondylitis, psoriatic arthritis, Crohn disease, asthma and multiple sclerosis." (PMID 34421907, 2021). "As is well reviewed elsewhere, genome wide association studies (GWAS) linked RUNX3 with diseases of inflammation in humans including ulcerative colitis, celiac disease, ankylosing spondylitis, psoriasis, and asthma." (PMID 29326930, 2017). "Analyses of methylation status of 2484 genes that were also correlated with expression levels led to the identification of asthma-associated CpG markers in RUNX3, IL4, and CAT." (PMID 28774304, 2017). "Immune deficiencies in Runx3-/- mice were also reported to cause lung inflammation associated with accumulation of hyper-activated DCs, leading to development of major hallmarks of asthma." (PMID 32453801, 2020). "Thus it is interesting to note that human genome-wide association studies have linked RUNX3 to various immune-related diseases including asthma, ankylosing spondylitis, psoriasis, psoriatic arthritis, atopic dermatitis and gastrointestinal tract (GIT) diseases such as celiac and Crohn’s disease." (PMID 32453801, 2020). "In fact, hypermethylation at RUNX3 loci triggered differentiation of T cells toward a Th2 phenotype that promoted asthma induction in mice." (PMID 41010514, 2025). "Similar to the results presented above, expression of Runx3 in BECs decreased in the asthma group, which was further lowered with Runx3 knockdown." (PMID 38774754, 2024). "The expression of Runx3 in BECs increased significantly in asthma+DHT+E2 and asthma+DHT groups compared with asthma group." (PMID 38774754, 2024). "The inhibition of miR-145-5p in T CD4+ cells from patients with asthma promoted an enhanced percentage of IFN-γ+ CD4+ T cells by regulation of RUNX3; thus, miR-145-5p can modulate the Th1/th2 balance in asthma." (PMID 38337625, 2024). "Some of the genes that were differentially methylated were observed to be differentially methylated in other studies of asthma as well, such as RUNX3 and IL4." (PMID 39380119, 2024). "We applied both IHC and Western Blotting to detect the expression of Runx3 in the lungs of mice with experimental asthma." (PMID 38774754, 2024). "Notable genes that were differentially methylated based on asthma severity included RUNX3, several members of the HLA family, AGT, PTPRC, PTPRJ, and several genes downstream of the JAK2 and TNF signaling pathway." (PMID 39380119, 2024). "In the severe asthmatic children, the RUNX3 gene, as well as these three enhancers, were downregulated as compared to children with mild asthma." (PMID 39108895, 2024). "MiR-371 has been confirmed to have the ability to inhibit Runt-related transcription factor 3 (Runx3), a transcription factor that promotes Th1 differentiation, by combining the other four miRNAs, thereby modulating the Th1/Th2 balance in asthma." (PMID 35769905, 2022). "A recent review discussed the relationship between RUNX3 and asthma: reduction of RUNX3 function via RUNX3 hypermethylation or mislocalization of the protein (in the mouse model) was found to be connected with the pathogenesis of asthma." (PMID 34421907, 2021). "In patients with asthma, miR-371 targets the Runx3 gene and is related to the Th1 and Th2 response balance, and its increased expression is related to a higher Th2 response." (PMID 30517108, 2018). "One study comparing PBMC methylation changes of 97 inner-city children with persistent atopic asthma to 97 healthy controls found 81 differentially methylated regions, including hypomethylated immune genes in asthma (i.E. il13, RUNX3, TIGIT)." (PMID 28774304, 2017). "Additionally, in CD4+ T cells of asthma patients, miR-145-5p negatively regulates Runt-related transcription factor 3 (RUNX3), which is essential for T-helper cell differentiation." (PMID 40332077, 2025).
asthma (continued). "Four asthma related SNPs are located in the RUNX3 locus, three of these within a few kilobases distance from the enhancers, which might suggest a possible functional role for these enhancers." (PMID 39108895, 2024). "Moreover, Qiu Yu-Ying and collaborators found that CD4+ T cells from patients with asthma presented both an up-regulation of miR-145-5p and a down-regulation of Runt-related transcription factor 3 (RUNX3) expression compared with healthy controls." (PMID 38337625, 2024). "A recent study showed that the inhibition of miR-19a in a mouse asthma model attenuated inflammation and mucus production induced by Th1 cells, suppressed the Th2 inflammatory response, and repressed dendritic cell maturation by increasing RUNX3." (PMID 38337625, 2024). "Moreover, combination of DHT and E2 further enhanced the expression of Runx3 in the lungs of mice with experimental asthma." (PMID 38774754, 2024). "Hence, our study aimed to explore the potential regulatory mechanism of androgen and estrogen on asthma via modulating Runx3." (PMID 38774754, 2024). "Therefore, higher levels of this miRNA led to an inhibition of RUNX3 expression, which indicates that miR-145 is involved in the pathogenesis of asthma through the regulation of Th1/Th2 balance by targeting RUNX3." (PMID 31703106, 2019). "In addition, supplementation with dietary methyl donors, such as folic acid, might increase DNA CG methylation by suppressing the expression of immune genes, such as runt-related transcription factor 3 (Runx3), and promoting the development of asthma." (PMID 39065238, 2024). "In mice with experimental asthma, there were increased serum concentrations of estrogen and decreased serum concentrations of androgen, intervention with combination of androgen and estrogen alleviated airway inflammations, increased Runx3 expressions and elevated Th1 differentiation." (PMID 38774754, 2024). "EWAS of childhood asthma using PMBCs from the participants in the Inner-City Asthma Consortium identified several asthma-related genes such as IL13, IL4, and RUNX3 with differentially methylated regions (DMRs)." (PMID 35055381, 2022). "RUNX1 and RUNX3 influence the development and function of TH1, TH2, TREG, and TH17 cells, which regulate autoimmunity, asthma, allergic responses, and tumor immunity." (PMID 29326930, 2017). "The expression of Runx3 decreased drastically in asthma groups, administration of E2 did not significantly alter the expression of Runx3, while DHT markedly restored its expression." (PMID 38774754, 2024). "Epigenomic studies have identified methylation patterns specific to COPD (e.g., C10orf11 in lung), asthma (e.g., IL13, RUNX3, TIGIT in PBMCs) and IPF (e.g., CASZ1 in lung), although much work remains to characterize cell-specific changes and include more ARDS and PAH samples." (PMID 28774304, 2017). "TLE interacts with Runt-related transcription factor 3 (RUNX3; OMIM 600210) in a manner that may be directly relevant to asthma." (PMID 19714205, 2009).
colon carcinoma (23 papers, 2008 to 2024). "Further biochemical studies need to be followed up to investigate the mechanistic principles involved in RUNX3-mediated inhibition of EMT in colitis associated colon cancer." (PMID 32765634, 2020). "According to our findings, MLH1-methylated CIMP-H CRC was significantly associated with high frequencies of a proximal colonic tumor location and RUNX3/SOCS1 promoter methylation compared with MLH1-unmethylated CIMP-H CRC." (PMID 26883113, 2016). "The RUNX3 gene is localized at the 1p36 locus, a region believed to harbor one or more tumor suppressor genes, as loss of heterozygosity in this region is observed in gastric, breast, ovarian, and colon cancers." (PMID 36900240, 2023). "Furthermore, stromal expression of RUNX3 is associated with increased lymphocyte density, suggesting that RUNX3 is an important mediator during recruitment and activation of immune cells in colon cancer." (PMID 36900240, 2023). "In a previous study, we demonstrated that oxidative stress-inactivated RUNX3 participates in abnormal cell proliferation via Akt/β-catenin/cyclin D cascade activation in human colon cancer cells." (PMID 38683453, 2024). "In colon cancer, increased RUNX3 expression levels in tumor epithelial cells and stromal cells are independent predictors of a good prognosis." (PMID 38430423, 2024). "Src-mediated RUNX3 phosphorylation induces RUNX3 mislocalization in various cancers, including colon cancer." (PMID 38683453, 2024). "Previously, we documented that oxidative stress promoteed RUNX3 mislocalization via HDAC1-induced Src activation and RUNX3 expression inhibition via DNA methylation in colon cancer cells." (PMID 38683453, 2024). "This study addressed the impact of oxidative stress on the unusual localization of RUNX3 in colon cancer cells and examined the role of histone modification-related proteins and nuclear exporters in this process." (PMID 38683453, 2024). "In this study, a RUNX3 eukaryotic expression vector was introduced into colon cancer HT-29 cells, and the expression of RUNX3 mRNA and protein were detected by RT-PCR and western blot, taking advantage of its high specificity and sensitivity." (PMID 32184893, 2020). "In colon cancer cells, the Tle6 gene interacts with the gastrointestinal tumor suppressor RUNX3, increasing tumor cell proliferation, colony formation, cell migration, and xenograft tumorigenesis." (PMID 32823735, 2020). "In this manuscript, the eukaryotic expression vector of RUNX3 is introduced into colon cancer HT-29 cells." (PMID 32184893, 2020). "The RUNX3 plasmid vector was transfected into human colon cancer HT-29 cells by liposome-mediated transfection, while the empty vector and the blank group were used as the control group." (PMID 32184893, 2020). "The aberrant methylation of Runx3 is frequently detected in colon cancer cells, resulting in structural alterations and a decreased density of tumor crypts." (PMID 30897785, 2019). "Furthermore, we showed that oxidative stress suppressed RUNX3 expression and promoted translocation to the cytoplasm in colon cancer cells by increasing HDAC level." (PMID 38683453, 2024). "Our findings demonstrated that the cytoplasmic distribution of RUNX3 in colon cancer cells under oxidative stress can be targeted for the development of novel therapy, as well as serving as potential biomarkers for the prediction of the occurrence of colon cancer." (PMID 38683453, 2024). "EZH2-OE is the opposite trend to si-EZH2; The EZH2 gene may target regulatory RUNX3 regulation via that Wnt/β-catenin signaling pathway, hence affecting colon carcinoma cell proliferation, invasion, migration, and apoptosis." (PMID 38048186, 2023). "Furthermore, hypermethylation of RUNX3 is part of a panel of markers defining the CpG island methylator phenotype (CIMP) of colon cancer." (PMID 36900240, 2023).
colon carcinoma (continued). "Apart from EZH2 and RUNX3 genes expressions, proteins from colon cancer tissues and healthy tissues were histologically examined by our project group using immunohistochemical method and real time fluorescence quantitative reverse transcription-polymerase chain effect." (PMID 38048186, 2023). "RUNX3 can inhibit the invasion and metastasis of human colon cancer HT-29 cells, and the mechanism may be related to decreased expression of MMP-2 and MMP-9." (PMID 32184893, 2020). "In colon cancer, RUNX3 is thought to be a tumor suppressor gene." (PMID 19521519, 2009). "In addition, we show that stromal RUNX3 is correlated with TIL density in colon cancer." (PMID 36900240, 2023). "We present the first study that differentiates between expression of IRS-1 and 2, RUNX3 and SMAD4 in the tumor epithelial and stromal compartments of colon cancer patients." (PMID 36900240, 2023). "These co-expression analyses, combined with our observation of RUNX3 being predominantly expressed in TILs, indicate that RUNX3 plays an important role in TIL-mediated colon cancer suppression." (PMID 36900240, 2023). "In this study, we apply deep learning to digitized pathology images to explore compartment level expression and prognostic impact of IRS-1, IRS-2, RUNX3, and SMAD4 in resected tumors from 452 colon cancer patients." (PMID 36900240, 2023). "High expression levels of IRS1, RUNX3, and SMAD4 are positive prognostic factors in stage I–III colon cancer." (PMID 36900240, 2023). "We confirm previous studies reporting preserved RUNX3 and SMAD4 in the tumor epithelial compartment as positive prognosticators in colon cancer." (PMID 36900240, 2023). "In this study, we explore the expression and prognostic impact of IRS-1, IRS-2, RUNx3, and SMAD4 in colon cancer." (PMID 36900240, 2023). "In colon cancer cell, TLE6 interacts with the gastrointestinal tumor suppressor RUNX3, increasing tumor cell proliferation, colony formation, cell migration, and xenograft tumorigenesis." (PMID 34264011, 2021). "For the top colon cancer MEGs, the consistent tumor suppressor genes included MAP2K4, MAPK10, RUNX3, WNK2 (the four genes were identified by the TSGene 2.0 database), BECN1, FASN, NAT1, and NR3C2." (PMID 33273919, 2020). "IRG signature of AXIN2, CCL22, CLEC10A, CRIP2, RUNX3, and TRPM5 is a reliable prognostic predictor for colon cancer patients." (PMID 33401247, 2020). "Highly connected biomarkers (with degree centrality) were BRAF mutation (0.19) and methylation-related markers including CDKN2A (0.17), IGF2 (0.17), RUNX3 (0.17), CACNA1G (0.15), CRABP1 (0.15), and NEUROG1 (0.15) in the proximal colon cancer network." (PMID 28623901, 2017). "In total, 31 CpG sites, located in 8 different genes (RUNX3, MLH1, NEUROG1, CDKN2A, IGF2, CRABP1, SOCS1 and CACNA1G) were investigated in 64 distinct colon cancers and 2 colon cancer cell lines." (PMID 24466191, 2014). "Therefore, in this study, we investigated the correlation between RUNX3, HDAC, HMT, and nuclear exporter to determine the cytoplasmic distribution of RUNX3 in colon cancer cells under oxidative stress." (PMID 38683453, 2024). "Furthermore, we present novel data on the positive prognostic value of stromal RUNX3, SMAD4, and IRS-1 in colon cancer." (PMID 36900240, 2023). "Not surprisingly, co-expression analyses indicate that RUNX3 plays an important role in TIL-mediated colon cancer suppression." (PMID 36900240, 2023). "As for colon cancer, the DNA promoter area of RUNX3 is hypermethylated, and gene expression is absent." (PMID 38048186, 2023). "Based on weak to moderate correlations with tumor epithelial and stromal RUNX3, IRS-1, CD8+ TIL density, and stromal miR126, stromal SMAD4 expression in colon cancer is likely involved in complex interactions between tumor epithelial cells and different types of stromal cells." (PMID 36900240, 2023).
colon carcinoma (continued). "As previously reported, RUNX3 expression was observed in its nuclei of normal mucosa, while colon cancer cells did not express RUNX3." (PMID 19521519, 2009).
pancreatic cancer (23 papers, 2007 to 2024). "In pancreatic cancer, loss of RUNX3 expression leads to the upregulation of multidrug resistance proteins (MRP), consequently increasing resistance to gemcitabine and adversely affecting patient prognosis." (PMID 38430423, 2024). "Yet, paradoxically, RUNX3 appears to function as an oncogene in leukemia, basal cell carcinoma, ovarian cancer, head and neck cancer, and pancreatic cancer." (PMID 38240752, 2024). "RUNX3 has also previously been shown to be expressed in pancreatic cancer and to play a role in promoting immunosuppression." (PMID 38619621, 2024). "Recently, double-sided role of RUNX3 as both a tumor suppressor and as a tumor promoter has just been discovered in pancreatic cancer." (PMID 38172737, 2024). "The frequent epigenetic inactivation of RUNX3 in cancer and the paradoxical elevated RUNX3 expression in metastatic pancreatic cancer indicate that tight control of RUNX3’s activities are crucial for normal growth." (PMID 36766749, 2023). "Loss of function of KDM6A causes squamous-like metastatic pancreatic cancer through aberrant activation of super-enhancers at the loci of MYC and RUNX3 oncogenes and consequent MYC and RUNX3 over-expression." (PMID 38135679, 2023). "Transcription levels of RUNX1, RUNX2, and RUNX3 were all increased in most types of cancers, including breast, esophageal, head and neck, and pancreatic cancer." (PMID 34485309, 2021). "GAS1 is a tumor suppressor involved in hedgehog signaling and RUNX3 is a transcription factor that is lost in pancreatic cancer and modulates metastatic potential." (PMID 27323855, 2016). "Previous studies have reported that EZH2 downregulates RUNX3 by inducing histone H3 methylation in various human cancers such as gastric, bile duct, and pancreatic cancers." (PMID 26871294, 2016). "CpG island methylator phenotype (CIMP)-high status [three/four or more methylated promoters among CACNA1G, CDKN2A, IGF2, and RUNX3] was observed in 12% (34/283) of the pancreatic cancer cases." (PMID 25797243, 2015). "In conclusion, we have clearly demonstrated for the first time that RUNX3 is frequently methylated in primary pancreatic cancer tissues, frequent hemizygous deletion occurs at its locus in 1p36, and RUNX3-inactivated cases showed worse survival." (PMID 18475302, 2008). "Hypermethylation and LOH appear to be common mechanisms for inactivation of RUNX3 in pancreatic cancer." (PMID 18475302, 2008). "Similarly, Horiguchi's research confirmed the downregulation of RUNX3 expression in pancreatic cancer." (PMID 38430423, 2024). "Whittle and colleagues reported that Runx3 regulates a notable number of genes implicated in ECM functions, including Col6a1 and Spp1, to directly stimulate cell migration and dissemination and thereby promote metastasis in pancreatic cancer." (PMID 38240752, 2024). "The silencing of RUNX3 by hemizygous deletion or DNA hypermethylation and the resultant reduced expression of RUNX3 protein is common in many types of cancers, including bile duct, lung, and pancreatic cancers." (PMID 36231060, 2022). "Moreover, RUNX3 can act in both ways within pancreatic cancer cells depending on cellular background and functional read out." (PMID 29342962, 2018). "In conclusion, DEMON proved to be a helpful predictive tool in TFBSs analysis and, together with experimental results, suggests that RUNX3 may prove to be an important target TF in pancreatic cancer research." (PMID 21203558, 2010). "The aim of our present study was to determine whether the RUNX3 gene alteration might have a role in carcinogenesis in pancreatic cancer." (PMID 18475302, 2008).